CDNF (cerebral dopamine neurotrophic factor)
Diseases named in the same sentence as CDNF in open-access papers (continued):
Sharing a sentence is not in itself a finding about the gene and the disease.
Cerebral ischemia (5 papers, 2014 to 2023). Restriction of arterial blood supply to the brain associated with insufficient oxygenation to support the metabolic requirements of the tissue. "Consistent with this, early studies demonstrated that MANF rescues cerebral cortex neurons in a rat cerebral ischemia model, and CDNF alleviates damage to astrocytes caused by ER stress." (PMID 25343619, 2014). "Published data from our lab showed that CDNF has neuroprotective effects on cerebral ischemia through ER stress pathways." (PMID 35163360, 2022). "Compared to RADA16-I, CDNF exerted a significant neuroprotective effect on brain ischemia-reperfusion injury." (PMID 35163360, 2022). "In this study, we investigated both the expression profile of CDNF via cerebral ischemia and the protective effect of CDNF on ischemic brain injury." (PMID 29966219, 2018). "Our data provided the first evidence of the neuroprotective effects of CDNF against cerebral ischemia in MCAO rats." (PMID 29966219, 2018). "We also investigate the expression of CDNF in cerebral ischemia and in primary neurons treated with ER stress-inducing agents." (PMID 29966219, 2018). "Published data from our group demonstrated the neuroprotective effects of CDNF on cerebral ischemia and the oxygen-glucose deprivation (OGD) cell model, which may occur through ER stress pathways." (PMID 35163360, 2022). "Moreover, the neuroprotective effects of CDNF in both in vivo and in vitro models of cerebral ischemia were suggested to occur through UPR pathways as the expression of CDNF was increased both by focal ischemia in the rat brain and in primary cultured neurons." (PMID 36012764, 2022). "Our results provided new evidence of the neuroprotective effects of CDNF in cerebral ischemia and cells, which may occur through ER stress." (PMID 29966219, 2018). "CDNF has neuroprotective effects on cerebral ischemia and on the OGD cell model, and the protective mechanism of CDNF may occur through the ER stress pathway." (PMID 29966219, 2018). "Our data indicate that CDNF has neuroprotective effects on cerebral ischemia and the OGD cell model and the protective mechanism of CDNF may occur through ER stress pathways." (PMID 29966219, 2018). "In addition, CDNF had a significant neuroprotective effect on brain ischemia-reperfusion injury." (PMID 35163360, 2022). "There are no reported data on CDNF on NSCs in a cerebral ischemia model." (PMID 35163360, 2022). "The function of CDNF during brain ischemia is still not known." (PMID 29966219, 2018).
ischemia (5 papers, 2018 to 2024). A hypoperfusion of the BLOOD through an organ or tissue caused by a PATHOLOGIC CONSTRICTION or obstruction of its BLOOD VESSELS, or an absence of BLOOD CIRCULATION. "It was found that more CDNF-positive cells appeared in the peri-infarct tissue following 2 h of ischemia and 24 h of reperfusion compared with the sham group." (PMID 29966219, 2018). "Our data showed that the expression of CDNF was upregulated in the peri-infarct tissue at 2 h of ischemia/24 h reperfusion in the MCAO rats." (PMID 29966219, 2018). "The CDNF+/NeuN+ cells in I/R 24 h ischemia group increased significantly than in the sham group (10.41 ± 8.35% versus 0.65 ± 0.58%)." (PMID 29966219, 2018). "First, the characteristics of ischemia-induced CDNF expression in the cerebral cortex were investigated using immunohistochemical assays and Western blotting in MCAO rats." (PMID 29966219, 2018). "Based on the compelling in vitro and in vivo findings, the next logical step was to explore whether the attenuation of ischemia-induced platelet activation and oxylipin biosynthesis by CDNF could potentially mitigate ischemic brain damage following dMCAo." (PMID 39256999, 2024). "Interestingly, CDNF was shown to possess anti-inflammatory capacity by inducing the production of IL-10 that plays pivotal roles in neuroprotection after ischemia." (PMID 36792604, 2023). "Given that systemic treatment with CDNF reduced platelet-mediated inflammatory responses after cortical ischemic stroke, it demonstrated the capacity to decrease infarction volume, alleviate neurological deficits, and further mitigate ischemia-induced blood-brain barrier (BBB) disruption." (PMID 39256999, 2024). "Cerebral dopamine neurotrophic factor (CDNF) is an evolutionarily-conserved protein with protective effects on midbrain dopaminergic system and cortical neurons in the ischemia model." (PMID 35740467, 2022).
Huntington disease (4 papers, 2020 to 2023). Huntington disease (HD) is a rare neurodegenerative disorder of the central nervous system characterized by unwanted choreatic movements, behavioral and psychiatric disturbances and dementia. "Recently, CDNF administration was demonstrated to increase Bdnf levels in the hippocampus in a N171-82Q mouse model of Huntington’s disease." (PMID 37555005, 2023). "Considering this, GDNF and CDNF could be of particular interest for PD, NGF could be of particular interest for AD, and BDNF, because of its rich expression in the brain, could provide support for AD, PD, spinal cord injury, multiple sclerosis (MS), and Huntington’s disease (HD)." (PMID 37047292, 2023).
Alzheimer disease (3 papers, 2023 to 2024). A progressive, neurodegenerative disease characterized by loss of function and death of nerve cells in several areas of the brain leading to loss of cognitive function such as memory and language. "Interestingly, CDNF has been shown to improve long-term memory in both WT mice and APP/PS1 mice, modeling Alzheimer’s disease." (PMID 37555005, 2023).
amyotrophic lateral sclerosis (3 papers, 2022 to 2023). Amyotrophic lateral sclerosis (ALS) is a neurodegenerative disease characterized by progressive muscular paralysis reflecting degeneration of motor neurons in the primary motor cortex, corticospinal tracts, brainstem and spinal cord. "All three UPR pathways are downregulated upon CDNF treatment in SOD1 mice modeling amyotrophic lateral sclerosis (ALS)." (PMID 35129674, 2022). "Furthermore, a recent study demonstrated that CDNF administration attenuated activation of all three UPR pathways in motoneurons isolated from the superoxide dismutase (SOD)-G93A mice model of amyotrophic lateral sclerosis (ALS)." (PMID 37555005, 2023).
depression (3 papers, 2022 to 2024). "Circulating concentrations of CDNF were not altered in PD patients while MANF concentrations were significantly increased and positively correlated with the Beck Depression Inventory scoring, which is used to measure the severity of depression." (PMID 34907395, 2022).
diabetes (3 papers, 2021 to 2023). "Results showed that CDNF-deficient Manf−/− mice presented the same phenotypes of growth defect and diabetes as Manf−/− mice." (PMID 35129674, 2022). "Diabetes is the most dominating phenotype of Manf−/− mice, therefore we investigated the severity of this phenotype in Cdnf−/−::Manf−/− mice, as CDNF is also expressed in the pancreas." (PMID 35129674, 2022). "Protein levels of CDNF are increased in the pancreas of Manf−/− mice, but it does not rescue manifestation of diabetes." (PMID 35129674, 2022). "The finding of clearly reduced CDNF protein levels in Manf−/− serum can also be a consequence of hyperglycemia and diabetes, although this has not been reported before." (PMID 35129674, 2022). "However, it can be speculated that prolonged mild downregulation of MANF/CDNF may contribute to impairment of ER stress response, making cells more vulnerable for various insults and implicating in development and progression of various diseases, such as neurodegeneration or diabetes." (PMID 34575854, 2021).
hematoma (3 papers, 2023 to 2024). A hematoma is a collection of blood from a vascular structure into an extravascular space. "In addition, the deficiency in endogenous CDNF affects hematoma resolution, suggesting that the administration of exogenous protein will adopt this mechanism to have a therapeutic effect after ICH." (PMID 36792604, 2023). "In our previous study, CDNF was identified to promote hematoma-scavenging functions of brain myeloid cells to accelerate resolution of hematoma after collagenase-induced ICH." (PMID 39256999, 2024). "In particular, genetic ablation of CDNF markedly impaired hemorrhagic lesion resolution and downregulated Hmox1 transcription at the phase of hematoma accumulation." (PMID 36792604, 2023). "In this study, we first characterized the time course of endogenous CDNF expression within the peri-hematoma area in a rat model of hemorrhagic stroke." (PMID 36792604, 2023). "Lesion volume changes on T2 images during hematoma resolution were significant in the CDNF-treated group compared to the saline-treated group." (PMID 36792604, 2023). "Simultaneously, amelioration of oxidative stress and UPR by CDNF remodels the peri-hematoma milieu from a pro-inflammatory microenvironment to a pro-reparative one." (PMID 36792604, 2023). "Here, we first demonstrate that endogenous levels of CDNF change during disease progression, decreasing at hematoma accumulation stages and increasing at a later period of hematoma resolution." (PMID 36792604, 2023). "Using collagenase-induced ICH in rats, we investigated whether the expression of CDNF in peri-hematoma tissue was affected." (PMID 36792604, 2023). "Similarly, spectrophotometric measurement showed that hemorrhagic volume on day 3 post-ICH was markedly reduced in the ICH + rhCDNF group, suggesting that CDNF accelerates hematoma clearance." (PMID 36792604, 2023). "Importantly, we show that post-ICH delivery of CDNF accelerates hematoma resolution, mitigates secondary brain injury, and improves functional recovery." (PMID 36792604, 2023). "In the present study, we demonstrate that CDNF enhances expression of the scavenger receptors, CD36 and CD163 on activated microglia/macrophages at the hematoma accumulation stage." (PMID 36792604, 2023). "Although the duration of exogenous CDNF in blood circulation is relatively short, it still could increase the expression of CD163 and CD36 in the peri-hematoma area, implying that CDNF in the circulation could induce peripheral monocytes/macrophages to remove hematoma at the early stage of ICH." (PMID 36792604, 2023).
synucleinopathy (3 papers, 2021 to 2024). A neurodegenerative disease that is characterized by the abnormal accumulation of aggregates of alpha-synuclein protein in neurons, nerve fibers or glial cells. "Nonetheless, the interaction of CDNF with α-synuclein, modifying its aggregation, spreading, and associated behavioral alterations, provides novel insights into the potential of CDNF as a therapeutic strategy in PD and other synucleinopathies." (PMID 33940158, 2021).
Ataxia (2 papers, 2020 to 2023). Ataxia refers to impaired coordination of voluntary muscle movement. "CDNF improved motor coordination and decreased ataxia in QA-toxin treated rats, and stimulated the neurogenesis by increasing doublecortin (DCX)-positive and NeuN-positive cells in the striatum." (PMID 33154393, 2020). "Moreover, CDNF decreased the ataxia coefficient in Digigait test, and gait, which is part of the pathology of HD." (PMID 33154393, 2020). "The ataxia coefficient, which is usually increased in HD53 was significantly decreased in contralateral forelimb in the CDNF-group (two-way RM ANOVA treatment × time interaction f8,102 = 2.002, p = 0.053; treatment effect f1,102 = 0.055, p = 0.814; time effect f8,102 = 0.939, p = 0.487)." (PMID 33154393, 2020).
breast carcinoma (2 papers, 2017 to 2025). "Similarly, miR-7641 inhibition in MDA-MB-231 breast cancer cells upregulated RPS16, TNFSF10, MSRB3, CDNF, ZNF616, and NBEA, downregulated CUL3, and showed no remarkable changes for PIGC and the other genes." (PMID 28827731, 2017).
hemorrhagic stroke (2 papers, 2023 to 2024). A stroke caused by a bleed on the brain. "This study first investigated the association between endogenous CDNF levels and platelet biological function within the 24-h interval following hemorrhagic stroke." (PMID 39256999, 2024). "Our analysis revealed a significant decrease in the CDNF protein levels among patients with hemorrhagic stroke compared with healthy donors." (PMID 39256999, 2024). "Utilizing animal models and platelets from hemorrhagic stroke patients, our research demonstrates that human cerebral dopamine neurotrophic factor (CDNF) acts as an endogenous antagonist, mitigating platelet aggregation and associated neuroinflammation." (PMID 39256999, 2024). "Overall, these findings suggest that loss of CDNF decreases mRNA levels of Hmox1 at the early stage of ICH, but increases hematoma accumulation at 3 days post hemorrhagic stroke." (PMID 36792604, 2023). "These discrepancies might be attributed to CDNF predominantly suppressing the biological activity of platelets derived from hemorrhagic stroke patients." (PMID 39256999, 2024). "Therefore, CDNF could be a potential therapeutic to accelerate lesion resolution and improve functional recovery in hemorrhagic stroke patients, when used in parallel with current treatment practices." (PMID 36792604, 2023). "Using the ELISA technique, we quantified the levels of endogenous CDNF protein in platelet-rich plasma (PRP) samples collected from healthy individuals and traumatic hemorrhage and hemorrhagic stroke patients." (PMID 39256999, 2024). "Thus, we treated PRP samples from hemorrhagic stroke patients with various platelet activators (ADP, TRAP-6, collagen, or AA) and exposed them to different doses of CDNF (0.1, 1, or 10 μg/mL)." (PMID 39256999, 2024). "In addition, our previous study revealed that heme oxygenase-1 (Hmox1) is significantly downregulated in the hemorrhagic striatum of Cdnf−/− mice, indicating that the absence of CDNF reduces the induction of Hmox1 after hemorrhagic stroke." (PMID 39256999, 2024).
infarction (2 papers, 2024 to 2025). A localised pathological necrosis of tissue resulting from obstruction of the blood supply usually by a thrombus, an embolus, or vascular torsion. "In our previous study on cardiac context, we demonstrated that exogenously administered full‐length CDNF, but not CDNF‐ΔKTEL, protects cardiomyocytes from ER stress and I/R‐induced infarction in both isolated hearts and in vivo models." (PMID 40827505, 2025).
insulinoma (2 papers, 2022 to 2023). "MANF and CDNF protein–protein interactomes were characterized using affinity purification-mass spectrometry (AP-MS) in human embryonic kidney HEK293 and rat insulinoma INS1 cell lines induced to overexpress MANF or CDNF." (PMID 37555005, 2023). "The cell lines studied for the CDNF interactome differ in both the organism and the tissue that they originate from—the INS1 cell line is derived from rat insulinoma and used as a model for pancreatic islet beta cell function, and HEK293 is derived from the human embryonic kidney." (PMID 36012764, 2022).
intracerebral hemorrhage (2 papers, 2023). A cerebrovascular disorder characterized by bleeding into one or both cerebral hemispheres including the basal ganglia and the cerebral cortex. "Given that phagocytosis is required to eliminate the hematoma after intracerebral hemorrhage, we next want to investigate if CDNF can directly manipulate the phagocytic activity of microglia/macrophages under pathological condition." (PMID 36792604, 2023). "In a rodent model of intracerebral hemorrhage, by contrast, CDNF administration was shown to efficiently reduce expression of GRP78, ATF6α, ATF4, and CHOP in the hemorrhage area of the striatum." (PMID 37555005, 2023). "Furthermore, a recent study revealed that CDNF could also increase transcriptional activity of NRF2 in an experimental model of intracerebral hemorrhage." (PMID 37555005, 2023). "Although CDNF was shown to regulate UPR initiated by transducers IRE1α, PERK and ATF6 in the pathological condition, we found that mRNA levels of UPR markers Grp78, spliced Xbp1, Atf4, and Chop were not significantly different between WT and Cdnf−/− mice after intracerebral hemorrhage." (PMID 36792604, 2023).
ischemic stroke (2 papers, 2023 to 2024). A stroke disorder caused by obstruction of blood flow to the brain, due to thrombotic (local blood clot formation) or embolic (due to a blood clot or other material traveling from another site) event. "Meanwhile, CDNF, as an anti-inflammatory protein likely linked to lipid metabolism and platelet activity, might exert a broader systemic effect, and is implicated in platelet-mediated pathological mechanisms following ischemic stroke." (PMID 39256999, 2024). "While CDNF level was shown upregulated in the infarcted cortex, a significant reduction in CDNF mRNA levels was observed in peripheral platelets following ischemic stroke in male patients." (PMID 39256999, 2024). "Consistent with ex vivo findings, subcutaneous administration of CDNF in a rat model of ischemic stroke significantly reduces platelet activation, aggregation, lipid mediator production, infarct volume, and neurological deficits." (PMID 39256999, 2024). "In accordance with the aggregation response findings, a decrease in AA-induced, but not collagen- or P4-induced upregulation of P-selectin expression was observed in PRP obtained from rats that had experienced ischemic stroke and were treated with CDNF." (PMID 39256999, 2024). "In summary, oxylipin profiling suggests that systemic administration of CDNF after ischemic stroke blocks the production of oxylipins derived by all biosynthesis pathways including COX, LOX, and CYP450s matching with reduced cPLA2 activity." (PMID 39256999, 2024). "Finally, our work challenges these findings with an animal model of ischemic stroke that demonstrate systemic administration of CDNF, by attenuating platelet activation, aggregation responses, and TXA2 production, it therefore mitigates ischemic-induced brain injury and neuroinflammation." (PMID 39256999, 2024). "Overall, these findings suggest that CDNF has the potential to regulate the activated phenotype of platelets, thereby mitigating the aggregation responses of PRP in the context of ischemic stroke." (PMID 39256999, 2024).
schizophrenia (2 papers, 2018 to 2023). A major psychotic disorder characterized by abnormalities in the perception or expression of reality. "Furthermore, another SNP in the CDNF gene was discovered to be a susceptibility locus in schizophrenia." (PMID 37555005, 2023). "Interestingly, a SNP in the CDNF gene was associated with negative symptoms of schizophrenia patients in the study population." (PMID 37555005, 2023).
alcohol use disorder (1 paper, 2021). "Unlike GDNF and BDNF, the role of MANF and CDNF in addiction and, particularly, in alcohol use disorder has not be studied extensively." (PMID 34923968, 2021). "However, the role of MANF and CDNF in addiction and, particularly, in alcohol use disorder is not clear." (PMID 34923968, 2021).
Anxiety (1 paper, 2024). Intense feelings of nervousness, tension, or panic often arise in response to interpersonal stresses. "In this field, anxiety-like behavior had been previously detected only in CDNF-deficient D. rerio, but a direct modulatory effect of CDNF on anxiety and behavioral despair is reported for the first time here." (PMID 39408672, 2024).
cognitive deficits (1 paper, 2024). "Administration of ASA, CM, or a combination of both mitigated these hippocampal damages and cognitive deficits, elevated BDNF and CDNF levels, and alleviated the CA1 necrosis caused by EB." (PMID 39262160, 2024).
Hyperglycemia (1 paper, 2022). An increased concentration of glucose in the blood. "Due to the developing severe hyperglycemia in Manf−/− animals, mice were terminated by the age of 7 weeks and the life span of CDNF-deficient Manf−/− mice could not be investigated." (PMID 35129674, 2022).